IGHM (immunoglobulin heavy constant mu)
Description:
Constant region of immunoglobulin heavy chains. Immunoglobulins, also known as antibodies, are membrane-bound or secreted glycoproteins produced by B lymphocytes. In the recognition phase of humoral immunity, the membrane-bound immunoglobulins serve as receptors which, upon binding of a specific antigen, trigger the clonal expansion and differentiation of B lymphocytes into immunoglobulins-secreting plasma cells. Secreted immunoglobulins mediate the effector phase of humoral immunity, which results in the elimination of bound antigens. The antigen binding site is formed by the variable domain of one heavy chain, together with that of its associated light chain. Thus, each immunoglobulin has two antigen binding sites with remarkable affinity for a particular antigen. The variable domains are assembled by a process called V-(D)-J rearrangement and can then be subjected to somatic hypermutations which, after exposure to antigen and selection, allow affinity maturation for a particular antigen. [Isoform 1]: Constant region of secreted IgM (sIgM), also known as the Fc region of IgM antibody. Able to multimerize, forms high order polymers, mainly pentamers and occasionally hexamers, providing for multivalency and high avidity recognition of antigens. Natural sIgM are polyreactive and recognize conserved self- and pathogen-derived structures, whereas immune sIgM are secreted only upon exposure to pathogens and are antigen-specific. Both natural and immune sIgM are required for an efficient humoral immune response to infection (By similarity). Mediates sIgM effector functions mostly via Fc receptors and the complement system. On lymphoid cells binds high-affinity Fc receptor FCMR and promotes induction of an efficient neutralizing IgG response while maintaining tolerance to self-antigens. Recruits C1q complement component to initiate the classical complement pathway, facilitating the recognition and neutralization of pathogens by the host. Together with C1q and mannose-binding lectin promotes the phagocytosis of apoptotic cells by macrophages, ensuring the clearance of potential autoimmune epitopes from tissues (By similarity). Involved in mucosal immunity. It is transported by transcytosis across mucosal epithelium by PIGR and secreted on the apical side in complex with PIGR secretory component to scan mucosal lining for pathogens. IgM-antigen complexes undergo FCMR-mediated retrotranscytosis across mucosal M cells toward antigen-presenting cells in mucosal lymphoid tissues (By similarity). [Isoform 2]: Constant region of membrane-bound IgM, part of the B cell receptor complex (BCR). IgM BCR provides constitutive tonic signaling for B cell survival. Mediates pre-BCR signaling that regulates B cell selection and rearrangement of Ig genes via allelic exclusion.
Synonyms: AGM1; MU; VH
Tractability: Antibody: its Gene Ontology location is reachable by antibodies, with high confidence; UniProt places it where antibodies can reach, with medium confidence; UniProt predicts a signal peptide or a membrane-spanning region. PROTAC: its protein half-life has been measured.
Gene: Immunoglobulin constant (C) gene on chromosome 14 (105,851,705 to 105,856,218, reverse strand). Ensembl gene ENSG00000211899.
Subcellular location: Secreted (Isoform 1); Cell membrane (Isoform 2)
Pathways (Reactome):
Immune System: Antigen activates B Cell Receptor (BCR) leading to generation of second messengers; CD22 mediated BCR regulation
Disease: Potential therapeutics for SARS
Hemostasis: Cell surface interactions at the vascular wall
Gene Ontology:
Molecular function: immunoglobulin receptor binding; peptidoglycan binding; phosphatidylcholine binding; single-stranded DNA binding; antigen binding
Biological process: adaptive immune response; antibacterial humoral response; defense response to Gram-negative bacterium; innate immune response; B cell receptor signaling pathway; defense response; immune response
Cellular component: blood microparticle; cell surface; extracellular exosome; extracellular region; hexameric IgM immunoglobulin complex; pentameric IgM immunoglobulin complex; IgM immunoglobulin complex; plasma membrane; immunoglobulin complex
Gene-disease validity (ClinGen):
ClinGen rates the evidence that IGHM causes each of these diseases.
autosomal recessive agammaglobulinemia 1 (autosomal recessive): Definitive.
Homologues: Orthologues: macaque IGHM (86% identical), rabbit IGHM (71% identical), mouse Ighm (66% identical), rat Ighm (62% identical), pig IGHM (57% identical), dog IGHM (51% identical), tropical clawed frog ighx (39% identical). Paralogues in human: IGHG3 (27% identical), IGHG1 (27% identical), IGHA2 (26% identical), IGHG2 (26% identical), IGHG4 (26% identical), IGHA1 (26% identical), IGHE (26% identical), IGHD (22% identical), IGLL1 (10% identical), IGLL5 (9% identical), IGLC7 (8% identical), IGHV7-4-1 (8% identical), and 65 more.
Diseases named in the same sentence as IGHM in open-access papers:
IGHM is named in the same sentence as 39 diseases in open-access papers, as found by Europe PMC text mining. Sharing a sentence is not in itself a finding about the gene and the disease. The quoted sentences say what the papers report.
breast carcinoma (8 papers, 2015 to 2025). "The blast cells from the MRD − patients depicted the highest expression of IGHM, a gene associated with good prognosis in breast cancer, and IGFBP7, a marker of leukemia cell and chemosensitivity in AML." (PMID 37845689, 2023). "The IGHM gene is upregulated in breast cancer, where it notably influences the infiltration of CD20+ B cells and is linked to patient prognosis." (PMID 40918463, 2025). "Of them, a set of genes related to immune function, such as CXCL13, IGHM, IGLL3P, IGJ and IGKC, were up-regulated in young patients with breast cancer." (PMID 25990390, 2015). "We employed machine learning algorithms to screen six genes, BATF, CXCR3, GIMAP5, GPR8, IGHM, and ISG20, that have been extensively investigated in other cancers, including lymphoma, melanoma, leukemia, breast cancer, multiple myeloma, hepatocellular carcinoma, and lung cancer." (PMID 39559348, 2024).
agammaglobulinemia (4 papers, 2018 to 2025). A decreased level of serum immunoglobulins. "Agammaglobulinemia with other inherited pattern were also concluded: AR agammaglobulinemia was associated with mutations in several other genes such as IGHM, IGLL1, CD79A, CD79B, BLNK, PIK3R1, and TCF3 genes; AD-related agammaglobulinemia was also found with LRRC8A and TCF3 gene mutations." (PMID 36140582, 2022). "In view of this patient’s clinical presentation and agammaglobulinemia, the differential diagnosis includes autosomal recessive forms of the disease (such as defects in IGHM, IGLL1, CD79A/B, PIK3R1, PIK3CD), as well as, more rarely, XLA." (PMID 41327272, 2025). "The comparison of IGHD, IGHM and IGHG(1 to 4) gene expression in PBMCs from TTD1 patients and healthy controls showed reduced gene expression of IGH chain genes in the patients thus indicating transcriptional impairment in B-cells likely to result in antibody deficiency." (PMID 39055713, 2024).
COVID-19 (4 papers, 2021 to 2023). A disease caused by infection with severe acute respiratory syndrome coronavirus 2. "Immunoglobulin-encoding genes were markedly over-expressed in COVID-19 compared to HLTY and INFL, and peaked in OXY1/TUBE EARLY (“hill” pattern, e.g. IGHM, IGHA1, IGHG1, JCHAIN)." (PMID 34135895, 2021). "Our data reveal a dramatic increase in the expression of immunoglobulin encoding genes of most classes (IGHM, IGHA, IGHG) in COVID-19 compared to HLTY and INFL subjects, with a peak among OXY1 and/or TUBE-early patients." (PMID 34135895, 2021). "Additional profiling of immune response-related genes highlighted the preferential proximal PAS usage of immunoglobulin genes, such as IGHM, IGHG1, IGHG3, and IGHA2, especially in B cells and plasma cells of COVID-19 samples." (PMID 34376223, 2021). "Specifically, signatures of plasma cells (IGHG3, IGKC, IGHM, JCHAIN, IGHG2, IGKV4-1, IGLV3-1, IGHA1), activated fibroblasts (COL1A1, COL1A2, COL3A1), inflammatory cytokines (CXCL9, CCL18) and complement factors (C1QB, C1QC) dominated the DE genes for the COVID-19 lung sections." (PMID 37858234, 2023).
myeloma (3 papers, 2022 to 2026). "For each patient, the following category of MM was available: light chain only, IGHA+, IGHG+, or other (including IGHM+, IGHD+, and IGHE+ rare myelomas)." (PMID 41286079, 2026). "On the other hand, immunoglobulin heavy constant mu (IGHM) and butyrophilin subfamily 1 member A1 (BTN1A1) were downregulated in myeloma patients (top)." (PMID 35800053, 2022).
atherosclerosis (2 papers, 2021 to 2022). A disease characterized by the build-up of fatty material and calcium deposition in the arterial wall resulting in partial or complete occlusion of the arterial lumen. "Finally, IGHM is involved in primary defense mechanisms and has a wide variety of properties, allowing it to participate in different pathophysiologies, such as infection, inflammation, or atherosclerosis." (PMID 34357353, 2021).
Achalasia (1 paper, 2016). A disorder of esophageal motility characterized by the inability of the lower esophageal sphincter to relax during swallowing and by inadequate or lacking peristalsis in the lower half of the body of the esophagus. "Interestingly, in our results, IRF4 and BLIMP1 are important upstream regulators of genes down-regulated, such as XBP1, IGHM, CD79A, RORC, and IKZF2, stressing the implications of the immune-inflammation network in achalasia." (PMID 27511445, 2016).
cholangiocarcinoma (1 paper, 2022). A carcinoma that arises from the intrahepatic biliary tree (intrahepatic cholangiocarcinoma) or from the junction, or adjacent to the junction, of the right and left hepatic ducts (hilar cholangiocarcinoma). "Studies from other groups have found that IGHM is abnormally expressed in patients with conjunctivitis-related systemic lupus erythematosus and cholangiocarcinoma." (PMID 35745003, 2022).
endometrial cancer (1 paper, 2024). Primary or metastatic malignant neoplasm involving the endometrium (mucous membrane that lines the endometrial cavity). "However, there is evidence to suggest that endometrial cancers harbour more mutations in the IGHM protein, compared to cancers of other sites." (PMID 38513301, 2024). "A 5-biomarker panel of cervico-vaginal fluid derived proteins (HPT, LG3BP, FGA, LY6D and IGHM) predicted endometrial cancer with an AUC of 0.95 (0.91–0.98), sensitivity of 91% (83%–98%), and specificity of 86% (78%–95%)." (PMID 38513301, 2024). "Immunoglobulins, including the immunoglobulin heavy constant mu (IGHM), were identified as potential endometrial cancer biomarkers." (PMID 38513301, 2024).
endometriosis (1 paper, 2021). The growth of functional endometrial tissue in anatomic sites outside the uterine body. "Further research is needed to elucidate the role of this new target gene in endometriosis, and ITGA7, ITGBL1, SORBS1 and IGHM may be therapeutic target genes." (PMID 34409913, 2021). "IGHM might be a potential target gene for the recurrence of endometriosis; however, to date, there have been no studies on IGHM in the reproductive system." (PMID 34409913, 2021).
idiopathic pulmonary fibrosis (1 paper, 2015). Idiopathic pulmonary fibrosis (IPF) is a nonneoplastic pulmonary disease that is characterized by the formation of scar tissue within the lungs in the absence of any known cause. "Lending to its role in lung disease, IGHM was found to be down-regulated in idiopathic pulmonary fibrosis (IPF) whole blood samples versus normal samples." (PMID 25582225, 2015).
influenza (1 paper, 2017). An acute viral infection of the respiratory tract, occurring in isolated cases, in epidemics, or in pandemics; it is caused by serologically different strains of viruses (influenzaviruses) designated A, B, and C, has a 3-day incubation period, and usually lasts for 3 to 10 days. "For KLH-specific IGHM, only 4 different IGHV genes were detected (IGHV2S2, IGHV2S3, IGHV2S4, or IGHV4S1); likewise for influenza-specific IGHM, 4 IGHV genes were detected (IGHV2S2, IGHV2S3, IGHV2S4, or IGHV4S2)." (PMID 28520789, 2017).
neuroblastoma (1 paper, 2024). Neuroblastoma (NB) is the most common solid, extracranial childhood tumor. "Six characteristic genes (BATF, CXCR3, GIMAP5, GPR18, ISG20, and IGHM) were identified by machine learning, and these genes are associated with multiple immune-related pathways and immune cells in neuroblastoma." (PMID 39559348, 2024). "BATF, CXCR3, GIMAP5, GPR18, IGHM have lower expression in high-risk neuroblastoma patients." (PMID 39559348, 2024). "BATF, CXCR3, GIMAP5, GPR18, ISG20, and IGHM may serve as biomarkers that reflect the conditions of the immune microenvironment of neuroblastoma and hold promise in guiding neuroblastoma treatment." (PMID 39559348, 2024).
parasite infection (1 paper, 2023). "The overexpression of IGHM could activate the immune response during bacterial and parasite infection in Labrus bergylta." (PMID 36845093, 2023).
Prader-Willi syndrome (1 paper, 2021). "Within this shared run, four genes were detected: IGHM (Immunoglobulin heavy constant Mu), MKRN3 (Makorin finger protein 3), MAGEL2 (MAGE family member L2) and NDN (Necdin), located upstream of the Prader-Willi syndrome (PWS) region." (PMID 34695128, 2021).
psychosis (1 paper, 2024). "Interestingly, among these proteins, there were the Heparin cofactor 2, Immunoglobulin heavy constant mu, the platelet factor 4, Filamin-A and Actin, cytoplasmic 1, Thymosin beta-4 which locus maps within the deleted region of chromosome 22 and found to be strongly associated with psychosis." (PMID 38418685, 2024).
Sepsis (1 paper, 2025). Sepsis is defined as life-threatening organ dysfunction caused by a dysregulated host response to infection. "Furthermore, several immunoglobulin genes including membrane and secreted forms of IGHM, IGHG1 and IGHG2 were also reduced in sepsis patients." (PMID 41208955, 2025).
uveitis (1 paper, 2020). An inflammatory process affecting a part of or the entire uvea. "Overall, distinct clusters of uveitis cases (termed “JIA uveitis 2”) became apparent, characterized by distinct expression of IGHD, CCR7, IGHM and CD27." (PMID 33042130, 2020).
X-linked agammaglobulinemia (1 paper, 2020). X-linked agammaglobulinemia (XLA) is a clinically variable form of isolated agammaglobulinemia, an inherited immunodeficiency disorder (see this term), and is characterized in affected males by recurrent bacterial infections during infancy. "Fourth, genetic mutations of non-X linked agammaglobulinemia encoding for pre-BCR and/or BCR complex (such as IGHM, CD79a, CD79b, and IGLL1 genes) and for activating mTOR signaling (such as PI3KD and PIK3R1 genes)." (PMID 33013854, 2020).
tumor (15 papers, 2014 to 2025). "Top upregulated genes linked to humoural immune response, such as BPIFB1 and IGHM may play an critical roles in tumour development." (PMID 40847563, 2025). "IGHM, associated with B-cell receptor signaling, might modulate the immune response by promoting B cell activation and antibody production in NBL, which could influence tumor progression and response to therapy." (PMID 39559348, 2024). "Our results demonstrate the upregulation of C1R, C1S, C3, IGHM and CFB in poorly differentiated tumours, suggesting activation through the classical pathway." (PMID 40847563, 2025). "Of these 21, we focused on 5 proteins (YWHAE, PFN1, LCP1, IGHM, CD5L) that were enriched in external CNSL cohorts, thereby supporting their utility as CNSL-enriched tumor burden biomarkers." (PMID 40321620, 2025). "Compared with normal tissues, only SLURP1 was downregulated in tumor tissues, while the expression levels of DKK1, GAST, IGHM, IL12RB2, STC2, and TNFRSF4 were upregulated in tumor tissues." (PMID 39282247, 2023). "Many proteins involved in tumour cell differentiation, such as ribosomal protein 19 (RPS-19), lamin A/C (LMNA) and immunoglobulin heavy constant mu (IGHM), exhibited decreased expression upon cell treatment with activated PSC secretome." (PMID 30923340, 2019). "Increased expression levels of all isotype genes in the post-treatment tumor was noted, although IGHG and IGHM predominated." (PMID 29721177, 2018). "The expression of genes in tumours was low for CD3Z, CD8, CXCL13, SNAI2 and ESR1 (40-DCq <32) and moderate for IGHM, CD4, CXCL9 and FOXP3 (40-DCq 32–35)." (PMID 25970543, 2015). "While the potential tumor burden markers (YWHAE, PFN1, LCP1, IGHM, CD5L) are relatively abundant in CSF and have been previously implicated in various malignancies beyond CNSL, our study uniquely demonstrates their value in monitoring CNSL disease progression and treatment response." (PMID 40321620, 2025). "We also identified YWHAE, PFN1, LCP1, IGHM, and CD5L as potential tumor burden markers." (PMID 40321620, 2025). "The CD138+CD3+ tumor cells also expressed high levels of IGHM, CD27, and XBP1, but were absent of CD19, CD22, CD24, and CD10 expression." (PMID 36494694, 2022). "In line with our results, it has been shown that decreased protein levels in cancerous samples of A2M, C4BP and IGHM/MUCB disturb the otherwise protective role of these proteins and may abet tumor development." (PMID 32408476, 2020). "In paired comparisons of tumour vs normal mucosa IR gene expression (n = 144), there was a trend for higher expression of CXCL9 (Wilcoxon test, p = 0.05) and lower expression of CD3Z, CXCL13 and IGHM in the malignant tissue." (PMID 25970543, 2015).
infection (6 papers, 2021 to 2025). The state of being infected such as from the introduction of a foreign agent such as serum, vaccine, antigenic substance or organism. "In addition, some genes in B cells were upregulated in response to infection, including IGHM, JACHAIN, and ADARB1." (PMID 38020713, 2023). "From the perspective of AFB1 exposure, regardless of infection status, four proteins—OBF1, RBM34, IGHM, and EBP2—decline more readily in response to AFB1 compared to the DMSO control." (PMID 41016387, 2025).
cancer (3 papers, 2013 to 2024). A tumor composed of atypical neoplastic, often pleomorphic cells that invade other tissues. "By analyzing the immune landscape of NBL, we identified six genes - BATF, CXCR3, GIMAP5, GPR8, IGHM, and ISG20-with diagnostic and clinical significance in other cancers, but whose roles in NBL remain largely unexplored." (PMID 39559348, 2024). "When PanIN samples were compared to PDACs, the most commonly up-regulated genes in the cancers were POSTN, COL1A2, SULF1, FN1, IGHM, VCAN and XIST, and these down-regulated were PGC and PPY." (PMID 23372777, 2013).
IGHM also shares sentences with these, for which no sentence is quoted: melanoma (3 papers); periodontitis (3); Diabetes (2); leukemia (2); abdominal aortic aneurysm (1); arteritis (1); conjunctivitis (1); follicular lymphoma (1); hepatocellular carcinoma (1); hookworm infection (1); infectious disease (1); lung carcinoma (1); lung disease (1); lymphoma (1); metastatic tumors (1); multiple myeloma (1); systemic lupus erythematosus (1); viral infection (1).